LCP1 (lymphocyte cytosolic protein 1)
Diseases named in the same sentence as LCP1 in open-access papers (continued):
Sharing a sentence is not in itself a finding about the gene and the disease.
cancer (continued). "In addition, LCP1 has been found in nearly 70% of epithelial-derived cancers, suggesting that its expression contributes to metastatic capabilities of the transformed cells." (PMID 31007850, 2019). "Additionally, in our clinical samples, the cancer cells at the invasive front revealed strong immunoreaction for both LCP-1 and F-actin." (PMID 28230172, 2017). "To evaluate the status of LCP1 expression as a cancer-related gene, we conducted real-time quantitative reverse transcription polymerase chain reaction (qRT-PCR) and immunoblot analyses with nine OSCC-derived cell lines and human normal oral keratinocytes (HNOKs)." (PMID 28230172, 2017). "Our findings suggest that MS17 upregulated HSPPA9, LCP1 and MSN and downregulated TALDO1 in SW620 cells, which could affect the JAK-STAT signaling pathway and associated with apoptosis, proliferation, and immune response, resulting in anti-cancer effects." (PMID 38542474, 2024). "LCP1 is over-expressed in many different cancers and may be involved in cell mobility." (PMID 29317542, 2018). "L-plastin (PLS2, LCP1) is exclusively present in hematopoietic cell lineages under normal conditions, but is expressed ectopically in many malignant tumors." (PMID 36979385, 2023). "Lower expression of LCP1 protein was observed in xenografted OSCC cells compared to the siControl group, suggesting that siLCP1 was effectively loaded into cancer cells via octExosomes." (PMID 33723306, 2021). "Filamin A (FLNA), plastin-2 (LCP1), coronin-1A (CORO1A), and formin-like-1 (FMNL1) also affect cytoskeletal dynamics by modulating actin filaments which eventually prompt cancer mobility and invasion." (PMID 32326232, 2020). "The upregulation of factors like LCP1 (usually expressed in lymphocytes) and members of the GAGE cancer/testis antigen family are intriguing." (PMID 30918060, 2019). "We identified potential novel upstream regulators (e.g., CNOT7, SPDEF, MITF, and PAX5) controlling distinct clusters of genes within the HPV-host cell network as well as distinct factors (e.g., CPPED1, LCP1, and TAGLN) with essential functions in cancer." (PMID 30918060, 2019). "AURKB, HOXB7, KYNU, and LCP1 are strongly upregulated in CESC, with the first two also upregulated in multiple other cancer types." (PMID 30918060, 2019). "We also demonstrated that while dual ABCE1+ LCP1 downregulation did not affect cancer cell extravasation, it significantly decreased tumor growth and dissemination, and increased overall survival." (PMID 31007850, 2019). "Given the frequent localization of lcp1-positive presumptive macrophages to the invasive edge of zebrafish ONP cancers, we assessed the relative expression of matrix metalloproteinases (MMPs) and cathepsins (CTSs) in precancerous and cancer microenvironments versus the control microenvironment." (PMID 39511408, 2025). "Notably, the expression levels of LCP1 are not significantly related to the patient's age, cancer stage, tumor size, or lymph node involvement." (PMID 38977952, 2024). "Thus, our results based on functional network analysis and thus a predictive bioinformatic model could indicate that PRDX2, LCP1, OGN and TAGLN2 might impact the IPF progression through mechanisms common to cancer." (PMID 38322285, 2023). "Among the candidate RCC tumor markers, NNMT, LCP1, and NM23A showed the highest features insignificance of difference in patients, the highest specificity in RCC compared to healthy individuals and several other cancers, and the best performances in the combination assay." (PMID 32992891, 2020). "Moreover, computational prediction did not reveal gene fusions or any other physical relationship between ABCE1 and LCP1 that can explain their additive role in cancer progression (data not shown)." (PMID 31007850, 2019). "Although not known to be as structured as TPT1, LCP1 (lymphocyte cytosolic protein 1) is also over-expressed in many different cancers and may be involved in cell mobility." (PMID 29317542, 2018).
cancer (continued). "Lymphocyte cytosolic protein 1 (LCP1), a member of actin-binding protein of the plastin family, has been identified in several malignant tumors of non-hematopoietic sites, such as the colon, prostate, and breast." (PMID 28230172, 2017).
tumor (40 papers, 2012 to 2025). "In patients in which tumors were evaluable by only 1 modality (ie, CSF or MRI), LCP1 levels were consistently elevated, reflecting the superior sensitivity of CSF proteomics in monitoring tumor burden in general." (PMID 40321620, 2025). "Functional assays revealed that LCP1 expression promoted tumor growth in vivo and enhances proliferation, migration, invasion, and cisplatin resistance in vitro across four OSCC cell lines." (PMID 41044643, 2025). "LCP1 was initially isolated from fibroblasts of tumor patients and subsequently detected in various cell lines and solid tumor samples." (PMID 38977952, 2024). "Increasing evidence has proven that lymphocyte cytosolic protein 1 (LCP1) promotes tumor progression." (PMID 39588922, 2024). "In the TCGA-TNBC RNA sequencing data, LCP1 expression levels were higher in tumor tissues compared to normal breast tissues (P< 0.001)." (PMID 38977952, 2024). "Although LCP1 is widely expressed across all hematopoietic lineages, numerous tumor cells are highly up-regulated by LCP1." (PMID 36823662, 2023). "The high expression of LCP1 in tumor cells is closely related to tumor invasion and metastasis, and its abnormal expression can be used as an effective prognosis marker for tumors." (PMID 36574182, 2023). "Under normal circumstances, LCP1 is mainly expressed in hematopoietic cells, but it is also highly expressed in a variety of malignant tumor cells." (PMID 36574182, 2023). "LAIT also induced the expression of Fos, Jun, Ptprcap, and Lcp1, which are associated with T cell receptor (TCR) signaling, indicating that T cells in LAIT‐treated tumours are responding to their cognate antigens." (PMID 35808806, 2022). "We also confirmed by qPCR that a subset of these genes (Anxa10, Ctse, Mmp10, Mmp13, Lcp1) were consistently upregulated in shG9a tumor cells compared to controls." (PMID 30455465, 2018). "Furthermore, LCP1 is highly expressed in both subtypes, indicating its possible role in the tumor's immune processes." (PMID 38977952, 2024). "Studies indicated that LCP1 is crucial for the migration potential of lymphocytes and certain tumor cells, further proving LCP1's key regulatory role on cell morphology and behavior in adaptive and innate immune systems (including macrophages, B cells, T cells, and NK cells)." (PMID 38977952, 2024). "Therefore, we suggest that octExosomes treatment led to markedly suppression of tumor growth through downregulation of LCP1." (PMID 33723306, 2021). "Furthermore, in vivo analysis of dual ABCE1 and LCP1 knockdown resulted in significant tumor growth inhibition, decreased metastatic activity, and contributed to survival compared to either gene, separately." (PMID 31007850, 2019). "Interestingly, loss of RB1 has been associated with a poor response to hormone therapy, and expression of LCP1 has been proposed as a biomarker of advanced tumour stage and tumour severity." (PMID 29665859, 2018). "Consequently, LCP1 may play a dual role in tumor progression and thwarting cell death signals, potentially serving as an effective prognostic marker." (PMID 38977952, 2024). "Further analysis using the ESTIMATE algorithm indicated that high expression of LCP1 is significantly associated with higher ImmuneScore, StromalScore and ESTIMATEScore in TNBC samples, suggesting that high expression of LCP1 may reflect a more active tumor microenvironment." (PMID 38977952, 2024). "However, a trend was observed where later stages of tumor had lower LCP1 expression, suggesting that further validation with additional samples might be necessary due to insufficient sample size." (PMID 38977952, 2024). "Thus, the mechanism for aberrant expression of LCP1 may differ from tumor to tumor, and more studies are needed to better understand the important role of LCP1 including its phosphorylation in tumoral progression." (PMID 28230172, 2017).
tumor (continued). "The dual role of LCP1 as both a biomarker for MAIVC response and a tumor burden marker necessitates additional validation through prospective studies conducted in a more standardized manner." (PMID 40321620, 2025). "The study identified CSF-based proteomic biomarkers, particularly LCP1, that can classify MAIVC response and indicate tumor burden in CNSL patients." (PMID 40321620, 2025). "Second, although our in vitro data support the involvement of LCP1–IL-1β axis, in vivo validation using OSCC relapse models is essential to confirm its role in tumor recurrence and immune modulation." (PMID 41044643, 2025). "Mechanistically, LCP1 expression and phosphorylation were induced by EGFR signaling through PI3K/AKT and ERK pathways, and further enhanced tumor aggressiveness via JAK2/STAT3-mediated IL-1β production." (PMID 41044643, 2025). "Of these 21, we focused on 5 proteins (YWHAE, PFN1, LCP1, IGHM, CD5L) that were enriched in external CNSL cohorts, thereby supporting their utility as CNSL-enriched tumor burden biomarkers." (PMID 40321620, 2025). "Exosome-mediated siLCP1 delivery resulted in the downregulation of LCP1 in OSCC cells compared with control cells, triggering significant in vitro and in vivo tumor suppression." (PMID 39355533, 2024). "Koide and colleagues showed that LCP1 is upregulated in OSCC, and overexpression of LCP1 correlated with tumor size and lymph node metastasis in OSCC clinical samples." (PMID 39355533, 2024). "The total protein levels of LTF, LCP1, AZU1, and ENO1 were all shown to be downregulated in tumor tissues." (PMID 37304069, 2023). "Six proteins (LMNA, LCP1, HSPD1, CS, CA1, and ALB) were previously identified as differentially expressed between the tumor center and margin." (PMID 35512017, 2022). "A functional relationship was found between LCP1, ITGB2, and IKZF1, suggesting that these genes regulate tumor immunology in COAD by regulating MDSC infiltration." (PMID 36230637, 2022). "After demonstrating the additive effect of LCP1 KD and ABCE1 KD in vitro, we analyzed the functional roles of dual ABCE1 and LCP1 inhibition on tumor growth, disease progression, and overall survival in vivo." (PMID 31007850, 2019). "While the potential tumor burden markers (YWHAE, PFN1, LCP1, IGHM, CD5L) are relatively abundant in CSF and have been previously implicated in various malignancies beyond CNSL, our study uniquely demonstrates their value in monitoring CNSL disease progression and treatment response." (PMID 40321620, 2025). "Differences in LCP1 gene expression between noncancerous and tumor tissues in OSCC patients were assessed with paired t-tests, while differences between disease-free and recurrent groups were evaluated using unpaired t-tests." (PMID 41044643, 2025). "We also identified YWHAE, PFN1, LCP1, IGHM, and CD5L as potential tumor burden markers." (PMID 40321620, 2025). "The findings imply that LTF, AZU1, and ENO1 are related to tumor grade, while LCP1 is not substantially different among tumor stages." (PMID 37304069, 2023). "These experiments revealed that octExosomes were stable, effective for transferring siLCP1 into OSCC cells and LCP1 was downregulated in OSCC cells with octExosomes as compared with their counterparts, leading to a significant tumor-suppressive effect in vitro and in vivo." (PMID 33723306, 2021). "Several tumor marker candidates of RCC, including nicotinamide N-methyltransferase (NNMT), L-plastin (LCP1), and non-metastatic cells 1 protein (NM23A), were identified and verified." (PMID 32992891, 2020).
infection (8 papers, 2012 to 2025). The state of being infected such as from the introduction of a foreign agent such as serum, vaccine, antigenic substance or organism. "We therefore reasoned that lcp1 loss-of-function in zebrafish could compromise resistance to infection, particularly in the post-hatching stages when fry are free-swimming, but before their adaptive immune systems are fully mature." (PMID 29293625, 2018). "In order to investigate the presence of leukocytes at the site of infection in myd88-/- zebrafish, we performed Lcp1/L-plastin immunostaining at 4 dpi for visualization of all leukocytes." (PMID 33559740, 2021). "Mechanistically, infection with H. pylori induces GC cells to express LCP1 via the CagA‐activated ERK signalling pathway, which mediates the binding of SP1 to the LCP1 promoter." (PMID 40999796, 2025).
bacterial infections (1 paper, 2019). "LCP1 was found to be essential for macrophage production and control of pulmonary infection in mice, and LCP1 null mice had a profound immune defect in controlling bacterial infections due to a lack of activation of innate immune responses." (PMID 31182931, 2019).
prostate (1 paper, 2017). "Moreover, an oral broad-spectrum fluoroquinolone, enoxacin (ENX), controlled expression of LCP1 and led to similar phenotypes of LCP1 knockdown cells in prostate cancer." (PMID 28230172, 2017).
LCP1 also shares sentences with these, for which no sentence is quoted: cholangiocarcinoma (4 papers); chronic lymphocytic leukemia (4); bladder cancer (2); cervical cancer (2); Granuloma (2); leukemia (2); liver fibrosis (2); Anxiety (1); atrial fibrillation (1); B-cell NHL (1); benign tumors (1); calculus (1); chronic pancreatitis (1); chronic periodontitis (1); follicular lymphoma (1); follicular thyroid cancer (1); immune deficiencies (1); keratitis (1); lung fibrosis (1); metastasis (1); metastatic cancer (1); metastatic melanoma (1); myopathies (1); non-small cell lung carcinoma (1); Opportunistic infection (1); oral diseases (1); osteoporosis (1); pancreatic cancer (1); periodontal diseases (1); prostatic intraepithelial neoplasia (1).
A further 5 diseases each share a sentence with LCP1 in 1 paper.